COG7 (component of oligomeric golgi complex 7)
Description:
Required for normal Golgi function.
Synonyms: CDG2E
Tractability: Antibody: UniProt places it where antibodies can reach, with high confidence. PROTAC: ubiquitination databases record sites on it; its protein half-life has been measured.
Target class: Other cytosolic protein
Gene: Protein-coding gene on chromosome 16 (23,388,493 to 23,453,207, reverse strand). Ensembl gene ENSG00000168434.
Subcellular location: Golgi apparatus membrane
Subcellular location (Human Protein Atlas): Golgi apparatus
Pathways (Reactome):
Vesicle-mediated transport: COPI-mediated anterograde transport; Intra-Golgi traffic; Retrograde transport at the Trans-Golgi-Network
Gene Ontology:
Molecular function: protein binding
Biological process: glycoprotein biosynthetic process; Golgi organization; intracellular protein transport; protein localization to Golgi apparatus; protein localization to organelle; protein stabilization; retrograde transport, vesicle recycling within Golgi; retrograde vesicle-mediated transport, Golgi to endoplasmic reticulum
Cellular component: Golgi apparatus; Golgi membrane; Golgi transport complex; trans-Golgi network membrane
Genetic constraint (gnomAD): Loss-of-function variants: 42 observed, 83.46 expected, observed/expected ratio (o/e) 0.5, 90% interval 0.39 to 0.65. The upper end of that interval is the gene's LOEUF score, 0.65, which puts it in group 2 of 6, group 1 being the genes least tolerant of losing a copy. Missense variants: 835 observed, 944.58 expected, observed/expected ratio (o/e) 0.88, 90% interval 0.83 to 0.94. Synonymous variants: 348 observed, 389.15 expected, observed/expected ratio (o/e) 0.89, 90% interval 0.82 to 0.98.
Gene-disease validity (ClinGen):
ClinGen rates the evidence that COG7 causes each of these diseases.
COG7-congenital disorder of glycosylation (autosomal recessive): Definitive. COG7-CDG is a congenital disorder of glycosylation characterized by dysmorphism, skeletal dysplasia, hypotonia, hepatosplenomegaly, jaundice, cardiac insufficiency, recurrent infections and epilepsy.
Homologues: Orthologues: chimpanzee COG7 (99% identical), macaque COG7 (99% identical), dog COG7 (94% identical), pig COG7 (93% identical), mouse Cog7 (92% identical), guinea pig COG7 (91% identical), rabbit COG7 (91% identical), rat Cog7 (86% identical), tropical clawed frog cog7 (76% identical), zebrafish cog7 (67% identical), Drosophila melanogaster Cog7 (28% identical).
Diseases named in the same sentence as COG7 in open-access papers:
COG7 is named in the same sentence as 9 diseases in open-access papers, as found by Europe PMC text mining. Sharing a sentence is not in itself a finding about the gene and the disease. The quoted sentences say what the papers report.
cholestasis (2 papers, 2017 to 2023). Impairment of the bile flow caused by obstruction within the liver, or outside the liver in the bile duct system. "In CDG presenting with cholestasis (such as ALG8-CDG, COG6-CDG, COG7-CDG, CCDC115-CDG and ATP6AP1-CDG), nutritional interventions such as in other causes of cholestasis can be necessary." (PMID 29112118, 2017).
tumour (1 paper, 2021). "mRNA expression levels of COG subtypes depended on the tumour grade, especially COG4, COG5, COG6, COG7, and COG8." (PMID 34539936, 2021). "Similarly, high mRNA expression of 5 of all COG isoforms (COG2, COG3, COG5, COG6, COG7, and COG8) was also correlated with favourable OS of KIRC patients with tumour grade 2, grade 3, and grade 4, while patients with low mRNA expression of COG4 showed higher survival rate." (PMID 34539936, 2021).
COG7 also shares sentences with these, for which no sentence is quoted: Cerebellar atrophy (1 paper); congenital disorder of glycosylation (1); Failure to thrive (1); keratosis pilaris (1); microcephaly (1); neurologic disease (1); primordial dwarfism (1).